TNFRSF12A (TNF receptor superfamily member 12A)
Diseases named in the same sentence as TNFRSF12A in open-access papers (continued):
Sharing a sentence is not in itself a finding about the gene and the disease.
atherosclerosis (12 papers, 2014 to 2024). A disease characterized by the build-up of fatty material and calcium deposition in the arterial wall resulting in partial or complete occlusion of the arterial lumen. "The common mechanisms shared in both are linked with atherosclerosis signaling and inflammatory response with at least the following target genes: Tnfrsf12a, Pla2g2f, Il1f9, Col1a1, Col1a2, and Col3a1 in brain, while Tnfrsf12a, SELP, SELE, IL6, and IL1A in myocardium." (PMID 29681850, 2018). "Tumor necrosis factor receptor superfamily member 12a (Tnfrsf12a) and tripartite motif containing 72 (TRIM72) overexpression have been associated with atherosclerosis and diabetic cardiomyopathy, respectively." (PMID 31625260, 2020). "Ten key regulated genes (including Pla2g2f, Il1f9, Col1a1, Col1a2, and Col3a1 in the brain, while SELP, SELE, IL6, and IL1A in the myocardium, and Tnfrsf12a in both) are correlative with atherosclerosis signaling and inflammatory response." (PMID 29681850, 2018). "It is worth noticing that the ten SXNI-regulated genes in atherosclerosis signaling are also related to inflammatory response, especially the Tnfrsf12a gene, which was shared in both brain and heart tissues." (PMID 29681850, 2018). "In conclusion, our study showed that SXNI effectively protects brain and heart from I/R injuries via a common Tnfrsf12a-mediated pathway involving atherosclerosis signaling and inflammatory response." (PMID 29681850, 2018). "Furthermore, A study based on RNA-seq and network pharmacological analysis showed that SXNI effectively protects heart from injuries via a common Tnfrsf12a-mediated pathway involving atherosclerosis signaling and inflammatory response." (PMID 37790809, 2023).
ovarian cancer (12 papers, 2012 to 2025). A primary or metastatic malignant neoplasm involving the ovary. "In ovarian cancer cells, BMP2 promotes cell proliferation and self-renewal capacity via c-Kit induction as well as cell migration and invasion via EMT; these effects are TNFRSF12A/FN14-dependent, as silencing of FN14 suppresses BMP2 actions in ovarian cancer cells." (PMID 38256140, 2024). "The cell lines exhibiting the strongest co-expression of ADAM9, TNFRSF12A, and AXL were 2 ovarian cancer lines (OVCAR_8 and SK_OV_3), lung cancer line HOP_92, and several renal cancer lines, suggesting that these cell lines may be particularly active in degrading extracellular matrix." (PMID 22570691, 2012).
Stroke (12 papers, 2012 to 2025). Sudden impairment of blood flow to a part of the brain due to occlusion or rupture of an artery to the brain. "Among these DEGs, we focused on tnfrsf12a; the protein encoded by this gene, Fn14, can mediate the onset and progression of neuropathic pain and stroke by activating the NF-κB signalling pathway." (PMID 39271624, 2025).
Cerebral ischemia (11 papers, 2012 to 2025). Restriction of arterial blood supply to the brain associated with insufficient oxygenation to support the metabolic requirements of the tissue. "On the other hand, Tnfrsf12a expression in brain is regarded as a prognostic/predictive biomarker of brain metastasis, and protects neurodegeneration and cerebral ischemia." (PMID 29681850, 2018).
Obesity (11 papers, 2014 to 2025). Accumulation of substantial excess body fat. "Bacterial LPS-induced inflammation may induce TNFRSF12A expression via TNFα signaling; thus, the observed Tnfrsf12 overexpression may be induced by an extracellular stimulus, e.g., LPS derived from obesity-related gut bacterial species." (PMID 40497936, 2025).
prostate carcinoma (11 papers, 2012 to 2022). A carcinoma that arises from epithelial cells of the prostate gland. "Furthermore, through modulating the expression of MMP-9, the overexpression of TNFRSF12A can promote prostate cancer progression and result in poor treatment outcomes." (PMID 34917619, 2021). "TNFRSF12A is a transmembrane receptor that plays an essential role in cell proliferation, invasion, and migration of androgen-independent prostate cancer cells through its binding to the multifunctional cytokine tumor necrosis factor-like weak inducer of apoptosis (TWEAK)." (PMID 25050621, 2014). "Besides, TNFRSF12A acts as a drive factor in bone metastasis of prostate cancer." (PMID 30301189, 2018). "TNFRSF12A also participates in activating the JAK/STAT signaling pathway in non-small cell lung cancers and the NF-kB signaling pathway in prostate cancer." (PMID 33937046, 2021).
myocardial infarction (9 papers, 2013 to 2025). Gross necrosis of the myocardium, as a result of interruption of the blood supply to the area, as in coronary thrombosis. "Meeting all the cutoff criteria across all the data set analyzed, MAN2A2/TNFRSF12A/SPP1/CSNK1D/PLAUR/PFKFB3/CXCL16 (herein we termed it MTSCPPC signature) was identified as a novel pathological signature of myocardial infarction and was used for subsequent analyses." (PMID 35163208, 2022).
psoriasis (9 papers, 2011 to 2025). An autoimmune condition characterized by red, well-delineated plaques with silvery scales that are usually on the extensor surfaces and scalp. "Fibroblast growth factor inducible-14 (Fn14, or TNFRSF12A) is essential for the development of psoriasis." (PMID 40369189, 2025).
cardiac hypertrophy (8 papers, 2014 to 2024). "TNFRSF12A was also found to be highly inducible and to play a key role in the development of cardiac hypertrophy followed by HF." (PMID 38892912, 2024). "One of the regulatory molecular pathways in charge of the mediation of cardiac hypertrophy is the tumor necrosis factor receptor superfamily member (TNFSF12)/ tumor necrosis factor receptor superfamily member 12a (TNFRSF12a) system." (PMID 37691190, 2023). "In addition, the role of TNFSF12/TNFRSF12a as a positive regulatory factor in cardiac hypertrophy was verified in the experimental model of right ventricular hypertrophy." (PMID 37691190, 2023). "Tnfrsf12a has been shown to be an important inducer of cardiac hypertrophy." (PMID 35380160, 2022). "Under the induction of mechanical strain, TNFRSF12a exerts its feedforward function, activates the signal cascade promoting hypertrophy and inflammation, and enhances pathological cardiac remodeling, presenting as ventricular hypertrophy and decreased cardiac function." (PMID 37691190, 2023).
COVID-19 (8 papers, 2020 to 2025). A disease caused by infection with severe acute respiratory syndrome coronavirus 2. "High plasma levels of MSR1, as well as high CSF TNFRSF12A and IL-8 levels demonstrated the most robust association with COVID-19 severity." (PMID 36351919, 2022). "Of interest, DCN and TNFRSF12A were distinctly elevated in severe COVID-19, separating severe disease from moderate, while MCP-3 and HGF were found to increment with disease severity." (PMID 39767799, 2024). "Plasma IL-8, CSF TNFRSF12A and EZR were strongly associated with both Neuro-COVID class III development and WHO COVID-19 severity, highlighting their importance as potential predictive biomarkers 19,22,27–29." (PMID 36351919, 2022). "Interestingly, in moderate COVID-19, the ligand to TNFRSF12A, TWEAK, was significantly reduced compared to in controls, and although this was not significant, it was also reduced in the ICU group." (PMID 39767799, 2024). "Thus, it is conceivable that the previously reported cytokine storm in severe COVID-19 predisposes for lung fibrosis, as we found the TNF-α pathway to be involved through TNFRSF12A." (PMID 39767799, 2024). "In severe COVID-19, alveolar macrophages promote fibroblast proliferation and fibrosis via the TNFSF12-TNFRSF12A signaling pathway, and silencing TNFRSF12A effectively reverses these profibrotic effects." (PMID 40806851, 2025). "We found the combination of the following factors to be of most interest to follow up on in a larger cohort of post-COVID-19 patients: CXCL13, DCN, HGF, MCP-3 and TNFRSF12A." (PMID 39767799, 2024). "There were no signal inflows unique to either moderate or severe COVID-19 alone, whereas inflow through TNFRSF12A (due to TNFSF12) and ITGAX and ITGB2 (due to C3) drive outflows in only healthy controls." (PMID 39187683, 2024).
acute kidney injury (7 papers, 2016 to 2022). Sudden and sustained deterioration of the kidney function characterized by decreased glomerular filtration rate, increased serum creatinine or oliguria. "Recently, TWEAK/Tnfrsf12a axis was reported to regulate necroptosis and contribute to acute kidney injury." (PMID 35853848, 2022). "Recently, TWEAK/Tnfrsf12a axis was also reported to regulate necroptosis and contribute to acute kidney injury." (PMID 35853848, 2022). "TWEAK/Tnfrsf12a axis has been shown to induce RIPK1-dependent necroptosis and acute kidney injury, suggesting that ALF might be also mediated by TWEAK/Tnfrsf12a axis and RIPK1-dependent necroptosis." (PMID 35853848, 2022).
colon carcinoma (7 papers, 2017 to 2025). "Previous studies have shown that inhibition of TNF family member FN14 (gene: TNFRSF12A) in colon tumors decreases inflammatory cytokine expression and mitigates cancer-induced cachexia." (PMID 37761958, 2023).
gastric cancer (7 papers, 2021 to 2025). A primary or metastatic malignant neoplasm involving the stomach. "Given that STAD is a common subtype of gastric cancer, it is highly likely that TNFRSF12A also plays a critical role in the pathogenesis of STAD." (PMID 40391219, 2025). "In gastric cancer, TNFRSF12A activates the PI3K/Akt and NF-kB signaling pathways, contributing to tumor development." (PMID 40595248, 2025). "TNFRSF12A silencing was found to promote the stimulation and expansion of T cells and further inhibit the cell viability of gastric cancer cell lines." (PMID 37926766, 2023). "In gastric cancer, TNFRSF12A is involved in the activation of the PI3K/Akt and NF-kB signaling pathways, which ultimately leads to the development of gastric cancer." (PMID 33937046, 2021). "The results of immunohistochemistry showed that the protein expression levels of RBP7, DES, SPP1, VIP, and PRKCG in gastric cancer tissues were higher than those in normal tissues, while PNOC, TNFRSF12A, and TUBB3 proteins are less expressed in gastric cancer tissues than normal tissues." (PMID 35174205, 2022).
thyroid cancer (6 papers, 2021 to 2024). "TNFRSF12A can be used as a prognostic marker for thyroid cancer as it is associated with the progression of CC." (PMID 35392242, 2022). "TNFRSF12A was linked to aging and thyroid cancer and was also shown to be a PTC prognostic biomarker in yet another study." (PMID 34767591, 2021). "Given that TNFRSF10B, TNFRSF10C and TNFRSF12A are up-regulated in thyroid cancer tissues and correlate with macrophages." (PMID 39104814, 2024). "The results showed that eight key genes (NUAK2, TNFRSF10B, TNFRSF10C, TNFRSF12A, UNC5B, and PMAIP1) exhibited good diagnostic performance in differentiating between thyroid cancer patients and controls." (PMID 39104814, 2024). "As an aging gene, the decreased expression of TNFRSF12A in thyroid cancer indicates a poor prognosis." (PMID 36142828, 2022). "The PPAR signaling pathway, the insulin signaling pathway, and the mTOR signaling pathway may be the critical pathways for controlling TNFRSF12A in thyroid cancer." (PMID 36142828, 2022). "A study on TCGA data suggested that the downregulation of TNFRSF12A in thyroid cancer could be a potential molecular biomarker for the prediction of poor prognosis." (PMID 34917619, 2021). "TNFRSF10B, TNFRSF10C, TNFRSF12A, UNC5B, PMAIP1, and IL18 had increased expression in thyroid cancer tissues, while NUAK2 was decreased." (PMID 39104814, 2024).
diabetes (5 papers, 2017 to 2025). "Four genes (TNFRSF12A, MAP1B, EZR and YWHAZ) upregulated in donors with chronic pancreatitis were also upregulated in vimentin-positive α-cells in donors without diabetes or CF." (PMID 39836539, 2025).
heart failure (5 papers, 2013 to 2020). Inability of the heart to pump blood at an adequate rate to meet tissue metabolic requirements. "Tnfrsf12a also known as TWEAKR/FN14 is expressed at low basal levels in the heart and sustained expression of the receptor results in adverse cardiac fibrotic remodeling and heart failure as a result of sensitized inflammatory response." (PMID 33042024, 2020).
sarcopenia (5 papers, 2025). Progressive decline in muscle mass due to aging which results in decreased functional capacity of muscles. "In particular, we found that the gut microbiota‐modulated LPS could alleviate age‐associated sarcopenia by regulating the Tnfrsf12a/caspase‐8 signalling pathway via integrated multiomics analyses and in vivo and in vitro experiments." (PMID 39901379, 2025). "Thus, above results suggest that the LPS‐activated Tnfrsf12a/caspase‐8 pathway is involved in the mechanism by which melatonin relieves age‐related sarcopenia through the gut–muscle axis." (PMID 39901379, 2025). "Notably, melatonin preserves mitochondrial structural and functional integrity, attenuating age-associated myofiber atrophy and counteracting LPS-induced apoptosis via the TNFRSF12A/caspase-8 axis in sarcopenia models." (PMID 40563280, 2025).
asthma (4 papers, 2019 to 2025). "High levels of TNFRSF12A contribute to the pathogenesis of severe asthma." (PMID 40005151, 2025).
Insulin resistance (4 papers, 2013 to 2025). Increased resistance towards insulin, that is, diminished effectiveness of insulin in reducing blood glucose levels. "Scavenger Receptor Class A Member 5 (SCARA5), TNFRSF12A, GDF-8, and Related Modular Calcium Binding 2 (SMOC2) were associated with insulin resistance markers and steatosis grade." (PMID 39407757, 2024). "RBKS, but not SMPD1, was associated with metabolic and liver dysfunction markers, while SCARA5, TNFRSF12A, and SMOC2, but not GDF-8, were associated with insulin resistance markers, and steatosis grade in the OB group." (PMID 39407757, 2024). "MSR1, KYNU, and RBKS, but not SMPD1, were associated with metabolic and liver dysfunction markers, while SCARA5, TNFRSF12A, SMOC2, but not GDF-8, were associated with insulin resistance markers." (PMID 39407757, 2024).
liver diseases (4 papers, 2016 to 2023). "The liver diseases PSC, PBC and AIH are commonly associated with aberrant ductular regeneration and, consistent with this, we found increased Fn14 (TNFRSF12A) mRNA and protein levels and expression of Fn14 associated with CK19+ ductule‐like structures in end‐stage liver disease explants." (PMID 26924336, 2016). "In the present study, we analyzed the methylation level of TNFRSF12A in HCC and other liver diseases through data mining from publicly available databases." (PMID 31998364, 2019).
bladder cancer (3 papers, 2021 to 2025). "We found that TNFRSF12A, IL1R1, ELN and CYP26B1 were overexpressed in bladder cancer cell lines, while NR1H3 and ITIH4 were downregulated." (PMID 38216619, 2024).
brain tumors (3 papers, 2014 to 2024). "Nanoparticles bound to ITEM-4 exhibited minimal binding to extracellular brain components, extremely strong binding to TNFRSF12A, and increased uptake into brain tumor cells." (PMID 33937046, 2021).
cervical cancer (3 papers, 2022 to 2025). A primary or metastatic malignant neoplasm involving the cervix. "Furthermore, TNFRSF12A (TWEAK-R), NT5E (CD73), and TGFB1/TGFBR1 were genes where low expression was significantly associated with increased survival in both cervical cancer and HNSCC, demonstrating that high expression of these immune genes is detrimental to outcome." (PMID 36575316, 2023). "Furthermore, TNFRSF12A was found to act as a C2 ALOX5+ MCs and tumor cell key receptor in the communication pathway that plays a role in cervical cancer progression." (PMID 40391219, 2025).
cholestasis (3 papers, 2022 to 2024). Impairment of the bile flow caused by obstruction within the liver, or outside the liver in the bile duct system. "Taken together, our data provided solid evidence that TNFRSF12A deficiency attenuates cholestasis-induced hepatocyte pyroptosis." (PMID 36690641, 2023). "In this study, we first reported that hepatic TNFRSF12A expression was dramatically increased in human cholestasis, and its elevation was positively associated with cholestatic liver injury." (PMID 36690641, 2023). "Therefore, we sought to delineate the role of TNFRSF12A in cholestasis and its underlying mechanisms." (PMID 36690641, 2023). "Previous studies in the context of cholestasis demonstrated that bile acids induce TNFRSF12A expression, subsequently initiating hepatocyte pyroptosis through the nuclear factor κB (NF-κB)/CASP1/gasdermin (GSDMD) signaling pathway." (PMID 39232561, 2024). "To gain insight into TNFRSF12A-mediated hepatocyte pyroptosis in cholestasis, we performed mechanistic studies in PLC/RPF/5-ASBT cells with TCA or LPS (a positive control) treatment." (PMID 36690641, 2023). "Subsequently, the elevation of TNFRSF12A triggers hepatocyte pyroptosis by the NFκB/Caspase-1/GSDMD signaling in cholestasis." (PMID 36690641, 2023). "Nevertheless, this is the first report on deciphering the functional significance and regulatory mechanism of TNFRSF12A in human cholestasis." (PMID 36690641, 2023). "Taken together, we report, for the first time, that hepatic TNFRSF12A is dramatically increased in human cholestasis." (PMID 36690641, 2023). "Taken together, these data suggested that conjugated BAs induced the expression of TNFRSF12A in human cholestasis by enhancing the activity of c-Jun binding to the TNFRSF12A promoter." (PMID 36690641, 2023). "In summary, our findings have provided the first evidence that hepatic TNFRSF12A expression remarkably increased in human cholestasis and its elevation positively correlated with cholestatic liver injury." (PMID 36690641, 2023). "Meanwhile, elevated levels of TWEAK produced by infiltrated macrophages in cholestatic livers, can further enhance TNFRSF12A-initiated hepatocyte pyroptosis during cholestasis." (PMID 36690641, 2023). "Knockdown and overexpression studies provided multiple lines of evidence in support of a novel role for TNFRSF12A in the induction of hepatocyte pyroptosis in cholestasis." (PMID 36690641, 2023). "To date, however, the functional significance and regulatory mechanism of TNFRSF12A in hepatocytes and human cholestasis are poorly characterized." (PMID 36690641, 2023). "Intrigued by the findings in BDL and 0.1%DDC-fed mice, we examined the expression of TNFRSF12A in human cholestasis." (PMID 36690641, 2023). "In this study, we aimed to examine the expression of hepatic TNFRSF12A and delineate its functional role and regulatory mechanism in human cholestasis." (PMID 36690641, 2023). "Considering the most recent findings that hepatocyte pyroptosis contributes to cholestatic liver injury, we examined the correlation between hepatic TNFRSF12A and pyroptosis in human and murine cholestasis." (PMID 36690641, 2023). "We performed a correlation analysis between the TNFRSF12A mRNA levels and liver function tests to explore its functional role in human cholestasis." (PMID 36690641, 2023). "Recent studies also demonstrated that the expression of Tnfrsf12a is markedly elevated in hepatic progenitor cells in mouse models of cholestasis induced by BDL operation and 5-diethoxycarbonyl-1,4- dihydrocollidine (DDC) diet, implying its distinct role in cholestatic liver injury." (PMID 36690641, 2023). "Altogether, these findings indicated that hepatic TNFRSF12A expression was remarkably induced in cholestasis, and its dramatic increase may contribute to cholestatic liver injury." (PMID 36690641, 2023). "Interestingly, hepatic Tnfrsf12a is also upregulated in hepatic progenitor cells in BDL- or 0.1%DDC-induced mouse models of cholestasis." (PMID 36690641, 2023).